LINC01315 (long independently transcribed non-coding RNA 1315)
Synonyms: lnc-C22orf32-1; C22orf32-1
Gene: Long non-coding RNA gene on chromosome 22 (42,363,671 to 42,369,300, reverse strand). Ensembl gene ENSG00000229891.
Diseases named in the same sentence as LINC01315 in open-access papers:
LINC01315 is named in the same sentence as 17 diseases in open-access papers, as found by Europe PMC text mining. Sharing a sentence is not in itself a finding about the gene and the disease. The quoted sentences say what the papers report.
colorectal cancer (8 papers, 2021 to 2025). A primary or metastatic malignant neoplasm that affects the colon or rectum. "This research discovered the up-regulation of LINC01315 in CD133+/CD44+ colorectal cancer stem cells for the first time, indicating that LINC01315 might be associated with the stemness of colorectal cancer cells." (PMID 35470736, 2022). "LINC01315 is upregulated in colorectal cancer (CRC) and osteosarcoma (OS) and has been validated as a novel methylation-related prognostic biomarker in lung adenocarcinoma (LUAD) and laryngeal squamous cell carcinoma (LSCC)." (PMID 35392086, 2022). "As a result, CD133+/CD44+ colorectal cancer stem cell-derived exosomal LINC01315 was found to promote the proliferation, migration, and stemness of colorectal cancer cells." (PMID 35470736, 2022). "In this study, we explored the role of LINC01315 in colorectal cancer stem cells, and the effects of colorectal cancer stem cell-derived exosomal LINC01315 on the biological function of colorectal cancer." (PMID 35470736, 2022). "Nevertheless, how LINC01315-mediated stemness of colorectal cancer cells regulated the development of colorectal cancer still needs further exploration." (PMID 35470736, 2022). "In conclusion, colorectal cancer stem cell-derived exosomal LINC01315 promotes the proliferation, migration, and stemness of colorectal cancer cells." (PMID 35470736, 2022). "Genes interacted with LINC01315 in colorectal cancer were predicted by bioinformatics analysis." (PMID 35470736, 2022). "Nevertheless, how LINC01315 functions in the stemness of colorectal cancer and whether LINC01315 exists in colorectal cancer stem-like cell-derived exosomes remain dim, which are thus investigated in this research." (PMID 35470736, 2022). "Furthermore, LINC01315 is proven to be highly expressed in colorectal cancer and LINC01315 silencing suppresses the aggressive phenotypes of colorectal cancer cells." (PMID 35470736, 2022). "LINC01315 was also found to be correlated with DPEP1, KRT23, ASCL2, AXIN2, and DUSP4 in colorectal cancer." (PMID 35470736, 2022). "LINC01315 has been reported to be upregulated in nasopharyngeal carcinoma and colorectal carcinoma (CRC), and it may be a prognostic biomarker in triple-negative breast cancer (TNBC)." (PMID 34876056, 2021). "In contrast, LINC01315 shows notably higher expression levels in thyroid and colorectal carcinoma (CRC) compared to noncancerous tissues or normal cells." (PMID 39183398, 2024).
triple-negative breast carcinoma (5 papers, 2021 to 2024). An invasive breast carcinoma which is negative for expression of estrogen receptor (ER), progesterone receptor (PR), and human epidermal growth factor receptor 2 (HER2). "The study found that upregulating LINC01315, which was reversed by introducing LINC01315 interference RNA, significantly hindered key cellular processes in triple-negative breast cancer." (PMID 39183398, 2024). "Instead, the overexpression of LINC01315 predicted a worse outcome of triple-negative breast cancer." (PMID 36979404, 2023). "However, previous study showed that the expression level of Linc01315 was higher in triple negative breast cancer(TNBC) tissues compared with non-TNBC tissues, and high Linc01315 expression associated with better DFS in TNBC patients." (PMID 34676156, 2021).
breast carcinoma (3 papers, 2021 to 2022). "Patients with a high LINC01315 expression level are associated with worse clinical outcomes, and LINC01315 might be an independent prognostic predictor in breast cancer." (PMID 35322763, 2022). "LINC01315 is a newly recognized lncRNA, which is abnormally expressed in thyroid cancer, oral squamous cell carcinoma and breast cancer, and can promote the development of these cancers." (PMID 35470736, 2022). "Our study showed that Linc01315 expression level in breast cancer was significantly correlated with tumor subtype, the expression level of Linc01315 was higher in Luminal A and Her-2 subtype than in Luminal B and basal like subtype." (PMID 34676156, 2021). "High Linc01315 expression in breast cancer significantly correlated with worse DFS and OS." (PMID 34676156, 2021). "Furthermore, analyzing the disease free survival (DFS) and overall survival (OS) of these 282 breast cancer patients revealed that patients with lower Linc01315 expression level had significantly longer DFS (P = 0.002) and OS (P=0.019)." (PMID 34676156, 2021). "Linc01315 may represent an independent prognostic marker and therapeutic target in breast cancer." (PMID 34676156, 2021). "Expression of Linc01315 in 44 paired of breast cancer tissues and their adjacent normal tissues were then detected." (PMID 34676156, 2021).
oral squamous cell carcinoma (3 papers, 2021 to 2022). "However, downregulation of LINC01315 has been found in oral squamous cell carcinoma (OSCC)." (PMID 34876056, 2021). "In oral squamous cell carcinoma (OSCC), LINC01315 was downregulated and showed a dramatically inhibitory effect on the proliferation, migration, and invasion of OSCC cells, and dampened cell apoptosis." (PMID 35412954, 2022).
nasopharyngeal carcinoma (2 papers, 2021). A carcinoma arising from the nasopharyngeal epithelium. "A previous study speculated that Linc01315 could promote the proliferation, migration and invasion of nasopharyngeal carcinoma (NPC) cells, and reduced the apoptosis of NPC cells, resulting in facilitating the tumorigenesis of NPC." (PMID 34676156, 2021).
Colon Cancer (1 paper, 2022). "A total of two groups of cell lines: two knockdown cells (siLINC01315, siNC) and two overexpression cells (oeLINC01315, oeNC) were applied in in vitro experiments to study the role of LINC01315 in colon cancer." (PMID 35911752, 2022). "Moreover, LINC01315’s biological activity in colon cancer cells was also investigated." (PMID 35911752, 2022). "Amid the many candidates in our signature, we selected LINC01315, an entirely new lncRNA that has virtually never been reported in colon cancer." (PMID 35911752, 2022).
gastric cancer (1 paper, 2023). A primary or metastatic malignant neoplasm involving the stomach. "Among them, LINC01315, AP003392.1, AL590666.2, and HAGLR were highly expressed in gastric cancer tissues, while the expression levels of AP000695.2 and AL161785.1 in gastric cancer tissues were lower than those in normal tissues." (PMID 36979404, 2023).
glioma (1 paper, 2025). A benign or malignant brain and spinal cord tumor that arises from glial cells (astrocytes, oligodendrocytes, ependymal cells). "LINC01315 knockdown significantly inhibited the growth of glioma cells." (PMID 39962243, 2025). "To discern whether these effects were solely attributed to the YAPer-ORF protein or LINC01315 itself, we overexpressed YAPer-ORF or the corresponding full-length lncRNA in glioma cells." (PMID 39962243, 2025).
melanoma (1 paper, 2025). A malignant, usually aggressive tumor composed of atypical, neoplastic melanocytes. "Furthermore, the scRNA-seq data from GSE139829 indicated that LINC01315 was predominantly expressed in melanoma cells." (PMID 39962243, 2025).
cancer (6 papers, 2022 to 2025). A tumor composed of atypical neoplastic, often pleomorphic cells that invade other tissues. "LINC01315 has been implicated in the pathogenesis of multiple cancers, including thyroid, breast, and gastric." (PMID 39962243, 2025). "In this study, we integrated transcriptomic data from neurodevelopmental disorders and diverse sets of data from various cancers and identified LINC01315 as a unique shared gene." (PMID 39962243, 2025). "LINC01315, which encodes a small protein named YAPer-ORF, has emerged as a critical factor that promotes cell growth in cardiovascular development and cancer models, including UM." (PMID 39962243, 2025). "Meanwhile, dysregulated LINC01315 was also reported to play roles in the development of various malignant tumors." (PMID 35412954, 2022). "Previous studies mentioned several miRNAs that mediate the regulatory effect of LINC01315 in various cancer, such as miR-211, miR-205-3p, and miR-497-5p." (PMID 35412954, 2022). "In previous studies, the abnormal expression of LINC01315 was controversial in different cancers." (PMID 35412954, 2022).
tumor (4 papers, 2021 to 2024). "Furthermore, LINC01315 was also a tumor promoter of TNBC that modulated the progression of TNBC via modulating miR-876-5p/GRK5." (PMID 35412954, 2022). "Therefore, further investigations are needed to evaluate the specific function of miR-876-5p during the tumor promoter role of LINC01315." (PMID 35412954, 2022). "Here, the upregulation of LINC01315 was disclosed in TNBC, which was positively correlated with the crucial clinicopathological characteristic of TNBC patients, such as TNM stage, LNM status, and tumor size." (PMID 35412954, 2022). "In addition, LINC01315 and AC037198.1 were expressed at lower levels in tumor tissues than in adjacent normal tissues (p < 0.05)." (PMID 34876056, 2021).
LINC01315 also shares sentences with these, for which no sentence is quoted: endometrial cancer (1 paper); laryngeal squamous cell carcinoma (1); lung adenocarcinoma (1); osteosarcoma (1); papillary thyroid cancer (1); thyroid cancer (1).